TUG1 (taurine up-regulated 1)
Diseases named in the same sentence as TUG1 in open-access papers (continued):
Sharing a sentence is not in itself a finding about the gene and the disease.
tumor (continued). "Ki67 staining showed that TUG1 knockdown significantly decreased the proportion of proliferating (Ki67+) tumor cells." (PMID 27362796, 2016). "In this study, we found that the average level of TUG1 in GC tissues was significantly higher than in corresponding non-tumor tissues." (PMID 26913601, 2016). "TUG1 was significantly downregulated, and the TUG1 downregulation correlated with sex (p = 0.006), smoking status (p = 0.016), and tumor differentiation grade (p = 0.001)." (PMID 27485439, 2016). "Here, we detected TUG1 expression in CRC tumor tissues and corresponding adjacent normal mucosa tissues." (PMID 27421138, 2016). "By invitro data, we then showed that TUG1 overexpression significantly enhanced tumor-like characteristics by increasing the colony formation, migration, and invasion of CRC cells." (PMID 26856330, 2016). "To further explore the biological significance of TUG1 in tumor angiogenesis, we carried out matrigel-based capillary tube-formation assays by human umbilical vein endothelial cells (HUVECs) using the tumor cell-conditioned medium (TCM) from HuH-6 cells." (PMID 27362796, 2016). "Pervasive studies showed that TUG1 is aberrantly expressed and participated in tumor development and progression." (PMID 27421138, 2016). "We show that TUG1 knockdown significantly suppresses angiogenesis in vitro and in vivo and xenograft tumor growth in nude mice." (PMID 27362796, 2016). "The anti tumour effect and inhibitory activity against TUG1 expression mediated by TUG1-DDS were even stronger than those observed with a γ-secretase inhibitor (RO4929097, oral administration) in our model (P=9.237 × 10−3)." (PMID 27922002, 2016). "At the end of the experiment, tumor volume was reduced by 28% in TUG1 knockdown group compared with the control group, which was consistent with tumor weight reduction." (PMID 27362796, 2016). "There was an obvious positive correlation between increased TUG1 levels and deeper tumor invasion depth (6.6585±6.36480 versus 2.5940±2.93578, P=0.017) and advanced TNM stage (8.3053±7.91956 versus 4.3465±3.57530, P=0.001)." (PMID 26913601, 2016). "Treatment with TUG1-DDS markedly reduced tumour growth compared with control-DDS (CTRL-DDS) together with the downregulation of TUG1 expression (P=5.451 × 10–5)." (PMID 27922002, 2016). "Up to 16 days after injection, the average tumor weight in sh-TUG1 group (0.196 ± 0.092 g) was significantly lower than that in the control group (0.582 ± 0.060 g) (P < 0.01)." (PMID 26336870, 2015). "In NSCLC patients, TUG1 low expression was associated with high TNM stage, tumor size, and poorer overall survival." (PMID 26448935, 2015). "qPCR analysis was performed to detect the average expression of TUG1 in tumor tissues selected from mice." (PMID 26336870, 2015). "Noticeably, high TUG1 expression was significantly correlated with tumor size (P = 0.003) and advanced BCLC stage (P < 0.01)." (PMID 26336870, 2015). "TUG1 expression was up-regulated in HCC tissues and the higher expression of TUG1 was significantly correlated with tumor size and Barcelona Clinic Liver Cancer (BCLC) stage." (PMID 26336870, 2015). "In consistent with in vitro results, tumor growth in sh-TUG1 group was obviously slower than that in the empty vector group." (PMID 26336870, 2015). "In a cohort of 192 NSCLC patients, the lower expression of TUG1 was associated with a higher TNM stage and tumor size, as well as poorer overall survival (P<0.001)." (PMID 24853421, 2014). "The TUG1 downregulation was correlated with advanced pathological stage (P=0.002) and greater tumor size (P=0.003)." (PMID 24853421, 2014). "In our current study, we found that the average level of TUG1 in NSCLC tissues was significantly lower than those in corresponding non-tumor tissues." (PMID 24853421, 2014).
tumor (continued). "The median ΔCt value for TUG1 in tumor tissues was used to divide the samples into high (below the median, n=96) and low (above the median, n=96) TUG1 expression group, and the corresponding P-value was calculated by log-rank analysis." (PMID 24853421, 2014). "The low expression level of TUG1 in NSCLC patients was associated with advanced pathological stage and tumor size." (PMID 24853421, 2014). "Moreover, m6A‐modified lncRNA TUG1 negatively regulates anti‐tumor immunity by inhibiting CD8+ T‐cell activation in HCC." (PMID 41316520, 2025). "Combination therapy using TUG1-siRNA and anti-PD-L1 antibody significantly suppresses tumor growth." (PMID 41346602, 2025). "Co-treatment with Tug1-siRNA and Pdl1 antibodies effectively inhibits tumor growth." (PMID 40352941, 2025). "Therefore, TUG1-siRNA combined with PD-L1 antibodies can effectively suppress tumor growth, providing new targets and strategies for HCCimmunotherapy." (PMID 40352941, 2025). "Studies suggest that TUG1 expression may be altered in WT, potentially influencing tumor cell growth, migration, and invasion." (PMID 40722750, 2025). "METTL3-mediated m6A modification upregulates TUG1, promoting tumor immune evasion." (PMID 40352941, 2025). "Therefore, the mechanism of TUG1 in regulating tumor immune evasion is revealed and can inform existing strategies targeting TUG1 for enhancing HCC immune therapy and drug development." (PMID 38981064, 2024). "However, how TUG1 is upregulated and the effects on tumor immune evasion are incompletely understood." (PMID 38981064, 2024). "The reasons for different than expected results for HOTIAR, MEG3 and TUG1 (family) are unknown, but the different material analyzed (tumor tissue vs serum) should be taken into account." (PMID 38601651, 2024). "Moreover, M1‐like macrophages in the spleens and tumors of Tug1‐knockdown tumor‐bearing mice clearly increased." (PMID 38981064, 2024). "Similarly, the downregulation of Tug1 reduced both the tumor volume and tumor weight significantly in subcutaneous mouse models." (PMID 38981064, 2024). "The knockdown of Tug1 significantly inhibited tumor growth and metastasis." (PMID 38981064, 2024). "As Tug1 sponges miR‐141 and promotes Pdl1 in vitro, we further explored whether miR‐141 was involved in the regulation of tumor growth in vivo." (PMID 38981064, 2024). "Moreover, a combination of Tug1‐siRNA therapy with a Pdl1 antibody effectively suppresses tumor growth." (PMID 38981064, 2024). "Furthermore, to evaluate the role of Tug1 in the tumor metastasis of HCC, the lungs of the experimental mice were acquired and lung metastatic nodules were stained with hematoxylin‐eosin (H&E) staining." (PMID 38981064, 2024). "However, the role of Tug1 upregulation in the tumor immune microenvironments is incompletely understood." (PMID 38981064, 2024). "Further study on the mechanism of Tug1 in regulating tumor immunity may bring new hope for patients who suffer from HCC." (PMID 38981064, 2024). "Moreover, the Long non-coding RNAs (lncRNAs) TUG1 was found to epigenetically inhibit miR-34a expression through increasing EZH2 (enhancer of zest homolog 2) that promotes tumor progression and aggressiveness." (PMID 38361758, 2024). "Moreover, the combination of Tug1‐siRNA therapy with a Pdl1 antibody effectively suppressed tumor growth." (PMID 38981064, 2024). "As Tug1 sponges miR‐340 and promotes Cd47 in vitro, we further explored whether miR‐340 plays a critical role in regulating tumor growth in vivo." (PMID 38981064, 2024). "Additionally, as the phagocytic effect of macrophages on tumor cells was enhanced after blocking CD47, we explored and found that the knockdown of Tug1 in tumor cells dramatically enhanced the phagocytosis of co‐cultivated macrophages." (PMID 38981064, 2024). "Thus, MALAT1, LUCAT1, and TUG1 are associated with the survival of patients with LC; HOTAIR can serve as a biomarker of tumour progression; and NEAT1 is related to poor prognosis." (PMID 38203731, 2023).
tumor (continued). "Furthermore, TUG1 knockdown in vivo reduced tumor growth by increasing miR-128-3p expression and reducing YES1 expression." (PMID 36831169, 2023). "Furthermore, we confirmed the results in HCC tumor and paired normal tissue samples by using RT-PCR to measure TUG1 mRNA expression." (PMID 37813900, 2023). "Mices were injected into sh-TUG1-expressing Huh7 cells to construct tumor model in vitro." (PMID 37160972, 2023). "Also for this cell line, combination therapy resulted in significantly greater suppression of tumor growth than either TUG1 ASO or TMZ alone." (PMID 37607907, 2023). "In addition, IHC staining certificated that the RRAGD expression decreased in neoplasms from mice injected with sh-TUG1-expressing Huh7 cells." (PMID 37160972, 2023). "TUG1 has an important effect on tumor immune microenvironment of HCC." (PMID 37813900, 2023). "LncRNA taurine up-regulated 1 (TUG1) is critical to tumor drug resistance." (PMID 35014946, 2022). "Many studies have shown that TUG1 plays a significant role in tumor progression." (PMID 35237695, 2022). "In cancer cells, TUG1 could modulate tumour‐related genetic loci by recruiting and binding to PRC2 protein complexes and promote metastasis by affecting epithelial–mesenchymal transition." (PMID 35729773, 2022). "Moreover, siRNA downregulation of TUG1 expression shows antitumor activity in HCC cells by suppressing tumor progression, such as proliferation, migration, and invasion, as well as by enhancing the T cell-induced immune response both in vitro and in vivo." (PMID 35237695, 2022). "Thus, TUG1 promotes tumor growth and angiogenesis in HB by preventing miR-34a-5p from regulating VEGFA, which can cause TUG1 to be a possible therapeutic target for HB." (PMID 35179516, 2022). "In addition, we designed and screened siRNAs targeting the conserved region of TUG1 as RNAi drug candidates, which inhibited tumor growth and progression as well as improved T cell-induced antitumor immune activity both in vitro and in vivo." (PMID 35237695, 2022). "In the present study, we found that TUG1 showed low expression levels in DNMT1 high-expression cells suggesting that TUG1 may be a tumor suppressor in this system." (PMID 34660799, 2021). "Besides, TUG1 depletion inhibited tumor growth and the level of TRIB2 was clearly declined, but the expression of miR-542-3p was markedly increased." (PMID 34030715, 2021). "Higher expression of TUG1 was related to the depth of the tumor." (PMID 33954114, 2021). "The tumor growth rate of nude mice in the TUG1 downregulated group was significantly slower than that in the control group and the nude mice group with simultaneous downregulation of TUG1 and miR-29a." (PMID 34659578, 2021). "However, the distinction of TUG1 expression was observed in different clinical stage (HR = 4.66, 95%CI: 2.47–8.79, P < 0.001), tumor size (HR = 4.07, 95%CI: 2.33–7.12, P < 0.001) and distant metastasis (HR = 3.53, 95%CI: 1.20–10.41, P = 0.020)." (PMID 33639865, 2021). "A research indicated that TUG1 could regulate the tumor cell growth, and TUG1 could attenuate the inflammation during the progression of liver injury." (PMID 34039367, 2021). "Based on the data provided in this study, TUG1 is a tumor-promoting gene of HCC." (PMID 34659578, 2021). "In this study, a total of 57 articles (65 cohorts) were included to comprehensively analyze the role of TUG1 in 22 types of tumors from across the body, and the results provide more information for TUG1 as a tumor prognostic biomarker to be applied in clinical prognostic risk analysis." (PMID 33747256, 2021). "In this study, we collected specific data of TUG1 involvement in tumor progression and survival of patients with different types of tumors, and we analyzed and summarized whether TUG1 is suitable as a prognostic marker for these tumors." (PMID 33747256, 2021). "It has been found that lncRNA TUG1 is aberrantly expressed in a variety of malignant tumor tissues." (PMID 34793263, 2021).
tumor (continued). "Although multiple meta-analyses have suggested that TUG1 could be used as a tumor-related prognostic marker, most studies were conducted before 2017." (PMID 33747256, 2021). "Additionally, overexpression of TUG1 was found to be correlated with low-grade tumor differentiation, advanced tumor stage, positive lymphatic metastasis, and positive distant metastasis." (PMID 33747256, 2021). "A recent publication showed that in 27 paired ESCC tissues and adjoining normal esophageal tissues, TUG1 was conspicuously upregulated in cancer samples (p < 0.0001), and high TUG1 expression was correlated with tumor size (p = 0.032), TNM stage (p < 0.001), and lymph node status (p < 0.001)." (PMID 34771549, 2021). "Different from previous analyses, the high expression of TUG1 was positively associated with tumor TNM stage, tumor differentiation, lymph node metastasis, and distant metastasis, which further confirmed the meaningful prognostic value of TUG1 in various tumors." (PMID 33747256, 2021). "Furthermore, we found that the expression of TUG1 was closely related to the grade of the tumor from the database." (PMID 34659578, 2021). "This may be due to differences in tumor types, the number of cases, the patient sources, the detection methods, and the cut-off values of TUG1." (PMID 33747256, 2021). "The tumor level of Ki67 was also reduced dramatically in the sh-TUG1 plus 2 Gy group." (PMID 31918742, 2020). "The upregulation of miR-29c reverses the TUG1 knockdown-mediated inhibition of tumor growth." (PMID 32042268, 2020). "Interestingly, reduced tumor volume, tumor growth, and tumor weight observed in response to TUG1 knockdown in the KYSE-30 xenografts compared to the controls after irradiation of 2 Gy." (PMID 32947897, 2020). "Higher expression of TUG1 was associated with TNM stage, tumor size, and lymphatic metastasis." (PMID 33330110, 2020). "Up-regulated TUG1 contributes to tumor growth in laryngocarcinoma via miR-145-5p/ROCK1 pathway." (PMID 33061856, 2020). "Tumor xenografts were implemented to explore the role of TUG1 in vivo." (PMID 31920462, 2020). "Besides, lncRNAs, as an important tumor regulator, has been widely concerned due to its potential role in tumor development, progression, and metastasis, such as TUG-1, UCA-1, MALAT1 and so on." (PMID 31844718, 2019). "Finally, these in vivo findings were reproduced in vitro on xenografts of DDP resistant NSCLC cells in BALB/c mice following DDP treatment and we found the anti-tumor effect of TUG1." (PMID 31532756, 2019). "In limited studies of non-neoplastic diseases, the function of TUG1 was still uncertain." (PMID 31551710, 2019). "Furthermore, TUG1 knockdown significantly inhibited the proliferation and invasion of PC cells both in vitro and in vivo, while overexpression TUG1 promoted tumour cell proliferation, migration, and invasion." (PMID 30595764, 2018). "To shed additional light on this issue, we conducted an analysis investigating the clinical significance of TUG1 in human normal and cancerous tissues from prostate, and PCa cell lines, as well as the role of TUG1 in the regulation of tumor cell proliferation and invasion in vitro." (PMID 29967294, 2018). "TUG1 expression was significantly elevated in ESCC tumor tissues compared with normal tissues." (PMID 30519392, 2018). "Similarly, downregulation of MALAT1 and TUG1 was related to tumor size, microsatellite instability, and young age at diagnosis and recurrence interval." (PMID 30195762, 2018). "TUG1 directly targeted miR-29c, a tumour suppressor in several cancers." (PMID 30595764, 2018). "Furthermore, the downregulation of miR-29c abolished the TUG1 knockdown-mediated inhibition of tumour growth in vitro and in vivo; conversely, the upregulation of miR-29c enhanced the effects of TUG1 knockdown on PC cells." (PMID 30595764, 2018).
tumor (continued). "Moreover, TUG1 knockdown combined with DDP treatment led to a more distinct reduction on tumor growth, suggesting down-regulation of TUG1 enhanced the DDP sensitivity of ESCC cells in vivo." (PMID 30519392, 2018). "We observed that TUG1 directly targeted miR-29c, a tumour suppressor in several cancers." (PMID 30595764, 2018). "TUG1 has been considered as an oncogene in many tumor cells." (PMID 30287503, 2018). "Furthermore, statistical analyses revealed that high TUG1 expression in tumor tissues was significantly correlated with DM, advanced tumor stage and large tumor size." (PMID 28977959, 2017). "Thus high TUG1 expression appears predictive of poor OS, distant metastasis, advanced tumor stage and large tumor size." (PMID 28977959, 2017). "Similarly, numerous studies have reported that TUG1 contribute to proliferation and apoptosis in a variety of tumor cells." (PMID 29029461, 2017). "On the other hand, the potential tumor suppression function of TUG1 may be considered, for example, by its regulation of PTEN expression." (PMID 29657297, 2017). "We found that knockdown of TUG1 markedly reduced tumor growth compared with the control group." (PMID 29371936, 2017). "Taurine up-regulated gene 1 (TUG1) is a long non-coding RNA (lncRNA), has been reported that be dysregulated in various tumors, involved in proliferation and apoptosis in a variety of tumor cells." (PMID 29029461, 2017). "Tumor grew significantly more slowly in mice following combined drugs treatment and TUG1 knockdown." (PMID 28069000, 2017). "TUG1 has been proved to act as a tumor suppressor or oncogene in various cancers." (PMID 28376901, 2017). "Furthermore, multivariate analyses indicated that TUG1 expression, tumor stage, and intrahepatic metastasis were independent prognostic factors for both OS and DFS." (PMID 29371936, 2017). "A xenograft mouse model was constructed to observe the effect of TUG1 on tumor growth in vivo." (PMID 28376901, 2017). "We also performed qRT-PCR to detect the expression of TUG1 in tumor tissues selected from mice." (PMID 28069000, 2017). "TUG1 enhanced tumor-induced angiogenesis and VEGF expression via directly binding to the miR-299." (PMID 28969024, 2017). "Moreover, combined treatment with TUG1 knockdown and drugs led to an even further reduction in tumor volume." (PMID 28069000, 2017). "In addition, high TUG1 expression is significantly correlated with DM (OR = 4.22, 95% CI: 2.66–6.70, P < 0.001) and tumor differentiation (OR=2.45, 95% CI: 1.28–4.70, P = 0.007)." (PMID 29029461, 2017). "Additionally, radiation significantly blocked the tumor growth of mouse model, and the inhibitory effect was enhanced when combined with TUG1 knockdown." (PMID 28376901, 2017). "Therefore, this meta analysis was conducted to analyze available data to delineate the potential clinical application of lncRNA TUG1 on cancer prognosis, lymph node metastasis and tumor progression." (PMID 28548946, 2017). "Moreover, both tumor volume and weight were dramatically reduced in the sh-TUG1 group compared with the control group, together with the down-regulation of TUG1 expression." (PMID 29371936, 2017). "While we observed neither significant differential expression of TUG1 in UC cell lines, nor in sample set 1,nor a significant correlation between TUG1 expression and either tumour grade or stage, TUG1 was significantly increased in the set 2 TCGA cohort (p = 0.001)." (PMID 28430799, 2017). "The result revealed that patients with a high TUG1 expression level in tumor tissues may indicate an increased probability of lager tumor size." (PMID 28977959, 2017). "Downregulation of TUG1 significantly inhibited tumor growth." (PMID 28069000, 2017). "TUG1 knockdown significantly suppresses tumor angiogenesis, thereby inhibiting tumor growth." (PMID 27362796, 2016). "TUG1-miR-34a-5p-VEGFA network is involved in tumor angiogenesis." (PMID 27362796, 2016).